PGR (progesterone receptor)
Diseases named in the same sentence as PGR in open-access papers (continued):
Sharing a sentence is not in itself a finding about the gene and the disease.
breast cancer (continued). "The triple-negative breast cancer (TNBC) subgroup, which is estrogen-receptor (ER) negative, progesterone-receptor (PR) negative, and HER-2 negative, accounts for approximately 15–18% of breast cancers." (PMID 29383104, 2017). "We detected SOX11 expression in triple‐negative [ER–/progesterone receptor (PR)–/HER2–] and HER2+ breast cancer cell lines." (PMID 28707729, 2017). "There are cancers that do not display hormonal receptors (ER, PGR) or overexpress the HER2 receptor; these belong to a specific type breast cancer, termed triple negative (TNBC)." (PMID 28926932, 2017). "Triple negative breast cancer (TNBC) is a breast cancer subtype lacking expression of estrogen receptor (ER), progesterone receptor (PR), and human epidermal growth factor receptor 2 (HER2) and accounts for about 15–25% of total breast cancer patients." (PMID 28706483, 2017). "Gallen International Conference 2011 proposed that breast cancer positive for ER and/or PgR, negative for HER2 with a Ki67 labeling index of less than 14%, should be defined as luminal A breast cancer." (PMID 27631393, 2016). "Triple-negative breast cancers (TNBCs), which is clinically defined by the absence of ER, progesterone receptor (PR), or human epidermal growth factor receptor 2 (HER2), accounts for about 15∼20% of all newly diagnosed breast cancer cases." (PMID 26871469, 2016). "ERα-/ERβ+ breast cancers belong to the triple-negative breast cancer (TNBC) group, a subgroup of breast cancers characterized by the lack of expression of ERα, progesterone receptor, and human epidermal growth factor receptor-2 (HER-2)." (PMID 27486755, 2016). "Although not a driver for ESR1 and PGR levels in SKBR3 cells, there was a strong correlation between Cav3.2 and levels of these hormone receptors in breast cancers." (PMID 27034617, 2016). "Triple-negative breast cancer (TNBC), not expressing estrogen receptor (ER), progesterone receptor (PR) and human epidermal growth factor receptor 2 (HER2) accounts for 15-20% of all breast cancer cases." (PMID 27829216, 2016). "Triple-negative breast cancers (TNBCs), defined by lack of expression of estrogen receptor, progesterone receptor and HER2, account for 12–17% of breast cancers and are clinically perceived as a discrete breast cancer subgroup." (PMID 28721389, 2016). "Triple-negative breast cancer (TNBC), defined as the lack of expression of estrogen receptor (ER), progesterone receptor (PR), and human epidermal growth factor receptor 2 (HER2), accounts for approximately 20% of all breast cancers." (PMID 27447966, 2016). "Triple-negative breast cancer (TNBC) which lacks estrogen receptor (ER) and progesterone receptor (PR) expression and without human epidermal growth factor receptor 2 (HER2) amplification, accounts for 15–20% of breast cancers." (PMID 27494850, 2016). "For this purpose, we have used Triple-Negative Breast Cancer (TNBC) cells (which stain negative for estrogen receptor, progesterone receptor, and HER-2) and human mammary adipocytes." (PMID 27027351, 2016). "About 74% of BRCA1-related breast carcinomas, 23% of BRCA2-related breast carcinomas and 13% of sporadic breast carcinomas had triple negative phenotype lacking ER, PgR and HER2 expression (p < 0.001)." (PMID 27566577, 2016). "We applied DERA to identify key regulations in triple negative breast cancer (TNBC), which is characterized by lack of estrogen receptor, progesterone receptor and HER2 expression and has poorer prognosis than the other breast cancer subtypes." (PMID 25928379, 2015). "We engineered triple (estrogen receptor/progesterone receptor/HER2/neu) negative, invasive MDA-MB-231 and SUM149 human breast cancer cells to silence the expression of HIF-1α, HIF-2α or both isoforms of HIF-α." (PMID 26305551, 2015). "The proliferation induced by androgens has also been demonstrated in breast cancer cell lines (MDA-MB-453) AR, ER and PgR negative when incubated with the synthetic, not metabolized androgen, Mibolerone." (PMID 26039245, 2015).
breast cancer (continued). "Triple-negative breast cancer, which is characterized by the lack of expression of the estrogen receptor (ER), the progesterone receptor (PR), and the human epidermal growth factor receptor 2 (HER2), is a type of breast cancer with aggressive tumor behavior." (PMID 25888956, 2015). "Triple-negative breast cancers (TNBCs), which do not express estrogen receptor or progesterone receptor, or overexpress HER2, are a particularly aggressive subtype of breast cancer characterized by high rates of metastases and poor prognosis." (PMID 26000098, 2015). "Triple-negative breast cancer (TNBC) characterized by the absence of estrogen receptor alpha (ER) and progesterone receptor (PR) expression and HER2 overexpression is mostly basal-like subgroup of breast cancers and accounts for 10%–20% of all breast cancers." (PMID 25695063, 2015). "Triple negative (ER, PgR and HER2 negative) breast cancers (TNBCs) are often considered as a poor prognostic phenotype." (PMID 24999743, 2014). "In the breast cancer dataset, there were significantly lower TIN-estimates in estrogen and progesterone receptor positive than negative samples (P = 0.04, independent samples t-test)." (PMID 25109687, 2014). "Next, we investigated Arg-pyrimidine accumulation in HER2 positive (SKBR3), estrogen/progesterone receptor-positive (MCF-7) and 4 triple negative (MDA-MB-231, MDA-MB-468, BT549, Hs579T) human breast cancer cell lines using Western blot analysis." (PMID 24978626, 2014). "Triple-negative breast cancers (TNBC), defined by the absence of estrogen receptor, progesterone receptor, and HER-2 expression, account for 12% to 24% of all breast cancers." (PMID 24632568, 2014). "Another type, which is negative for estrogen receptor (ER), progesterone receptor (PR), and HER-2—all used as biomarkers in breast cancer treatment—is defined as the triple-negative breast cancer (TNBC)." (PMID 24979213, 2014). "Approximately, 15–20% of all breast carcinomas are included in the subgroup of triple-negative breast cancer (TNBC) that are characterized by the lack of ERα, progesterone receptor (PR), and EGFR 2 (Her-2)." (PMID 24834064, 2014). "Breast tumors that were negative for estrogen receptor, progesterone receptor and HER2 gene amplification, otherwise known as “triple negative” breast cancers also strongly expressed CT-X antigens compared to receptor-positive tumors." (PMID 23935846, 2013). "Our data confirmed that anthricin markedly induced apoptosis in 2 breast cancer cell lines, MCF7 (estrogen receptor positive) and MDA-MB-231 (estrogen receptor, progesterone receptor, and Her2/Neu receptor negative)." (PMID 23818925, 2013). "This cell line is characterized as triple-negative status (estrogen receptor negative, progesterone receptor negative, and HER2 negative) and classified as the basal-like subtype of breast cancer." (PMID 24204647, 2013). "In metastases of breast cancer to the lung pleura, the percentage of blood vessels expressing FSHR was positively correlated with the progesterone receptor level, but not with either HER-2 or estrogen receptors." (PMID 23688201, 2013). "In our study, we employed a mouse model of lung metastasis with the human breast cancer cell line MDA-MB-231, which is a triple negative cell line lacking expression of the oestrogen receptor (ER), the progesterone receptor (PR) and the Her2 receptor (HER2)." (PMID 22509065, 2012). "We therefore investigated the relationship between CD44 and hypoxia in triple (estrogen receptor, progesterone receptor and Her2/neu) negative (ER, PR, Her2/neu negative) MDA-MB-231 and SUM-149 human breast cancer cells." (PMID 22937154, 2012). "There are no obvious differences in estrogen and progesterone receptor expression nor HER2 expression between viral positive and negative fresh breast cancer specimens." (PMID 23183846, 2012).
breast cancer (continued). "The aim of this study was to compare the correlation of immunohistologically measured Ki 67 protein expression with the Oncotype Dx RS in patients with lymph node-negative ER/progesterone receptor (PR)-positive, HER-2-negative breast cancers." (PMID 21970880, 2011). "In sum, the loss of HDAC1 and HDAC2 increases C3 and NCOA2, but not CLU, ERBB2, MYC, or PGR, providing evidence that C3 and NCOA2 are repressed in breast cancer cells by the HDAC1/2 components of the Sin3A repressive complex." (PMID 20920219, 2010). "We therefore investigated the changes in cellular viability as well as the expression of the ERα-responsive downstream gene, progesterone receptor (PGR), in ERα-negative MDA-MB-231 breast cancer cells with treatments of EGCG and TSA alone or together." (PMID 20946668, 2010). "Several studies have demonstrated that the breast cancers in women who have used HRT are more frequently estrogen receptor and progesterone receptor positive than in those who have not used HRT." (PMID 19538720, 2009). "A new entity, the so-called triple negative (oestrogen receptor, progesterone receptor and HER2 negative) breast cancer has a highly aggressive clinical course with shorter recurrence-free and overall survival." (PMID 19293801, 2009). "As a result of these advances, a breast cancer cluster with poor prognosis that is negative for the estrogen receptor (ESR1), the progesterone receptor (PRGR) and ERBB2 (triple negative) has come to the forefront of medical therapeutic attention." (PMID 19007432, 2008). "One well-defined subtype of breast cancer is characterized by a lack of HER2 gene amplification and estrogen and progesterone receptor expression ('triple-negative tumors')." (PMID 17910759, 2007). "Ten patients with advanced breast cancer whose tumors overexpressed HER-2, but not ER or PgR, were treated with weekly trastuzumab at standard doses with or without chemotherapy." (PMID 16417653, 2006). "The only other laboratory that studied PMN-E expression in human breast cancer tissues reported a nonsignificant trend towards a negative correlation between PMN-E levels and those of ER and PgR in a small series of 62 tumours." (PMID 12671709, 2003). "Triple-negative breast cancer (TNBC), which is characterized by a lack of the estrogen receptor, the progesterone receptor, and HER2 expression, is the most aggressive breast cancer subtype and has a poor prognosis and high recurrence rates because of frequent chemotherapy resistance." (PMID 41595775, 2026). "Case Presentation: A 72-year-old woman with a history of Estrogen Receptor (ER)-positive (5%), Progesterone Receptor (PR)-negative, Human epidermal growth factor receptor-2 (HER2)-negative breast cancer (diagnosed 3 years prior) presented with right orbital pain, diplopia, and periorbital swelling." (PMID 42238014, 2026). "Unlike other breast cancer subtypes, triple-negative breast cancer (TNBC) lacks the expression of estrogen receptor (ER), progesterone receptor (PR), human epidermal growth factor receptor 2 (HER-2), making it unresponsive to hormonal and HER2-targeted therapies." (PMID 41295383, 2025). "Due to the absence of estrogen receptor (ER), progesterone receptor (PR), and human epidermal growth factor receptor (HER2) expression, TNBC patients face poor prognoses and limited treatment options compared to other breast cancer subtypes." (PMID 40820992, 2025). "Additionally, the effects of VC were evaluated in MCF cells, which are estrogen and progesterone receptor-positive, HER2/neu receptor-negative, and considered a less invasive form of breast cancer." (PMID 40149617, 2025). "Breast cancer, a prevalent global health concern, has sparked extensive research efforts, particularly focusing on triple negative breast cancer (TNBC), a subtype lacking estrogen receptor (ER), progesterone receptor, and epidermal growth factor receptor." (PMID 39021344, 2025).
breast cancer (continued). "Triple-negative breast cancer (TNBC) is distinguished by negative expression of estrogen receptor (ER), progesterone receptor (PR), and human epidermal growth factor receptor 2 (HER2), making it an aggressive subtype of breast cancer and contributes to 15-20% of the total incidence." (PMID 39450256, 2024). "As an aggressive subtype of breast cancers, triple-negative breast cancer (TNBC) are defined by the lack of estrogen receptor (ER) and progesterone receptor (PR) and absence of human epidermal growth factor receptor 2 (HER2) protein overexpression and HER2 gene amplification." (PMID 38982161, 2024). "Notably, most basal-like breast cancer patients belong to the group of triple-negative breast cancer (TNBC), which is featured by a lack of estrogen receptor (ER), progesterone receptor (PR), and HER2." (PMID 37893115, 2023). "Finally, tumors categorized as Triple-Negative BC (TNBC), which are negative for HER2, ER, and PgR, are usually associated with mutations in the breast cancer 1 (BRCA1) gene and represent the most aggressive and invasive BC type, with a mean of survival rate of 13 to 18 months after diagnosis." (PMID 36986040, 2023). "BC could be clustered into molecular subtypes, including luminal, human epidermal growth factor receptor 2-positive (HER2+) and triple-negative breast cancer (TNBC) tumors based on the expression of the estrogen receptor (ER), progesterone receptor (PR), and the overexpression of the HER2." (PMID 37633945, 2023). "Accounting for approximately 15%-20% of instances of breast cancer (BC), triple-negative breast cancer (TNBC) is pathologically defined by a lack of targetable estrogen receptor (ER), progesterone receptor (PR), and human epidermal growth factor receptor 2 (HER2)." (PMID 36874102, 2023). "BRCA1 mutations are linked preferentially to the triple negative form of BC (estrogen receptor negative, progesterone receptor negative, and HER2 negative, TNBC), whereas BRCA2-associated breast cancers are generally estrogen receptor-positive, and phenotypically different (mostly luminal-like BC)." (PMID 36902416, 2023). "Triple-negative breast cancer (TNBC), defined by estrogen receptor (ER)-negative, progesterone receptor (PR)-negative, and human epidermal growth factor receptor-2 (HER2)-negative histological presentation, accounts for approximately 20% of all breast cancer cases." (PMID 37109526, 2023). "Triple-negative breast cancer (TNBC), a breast cancer subtype characterized by lack of estrogen and progesterone receptor expression and absence of EGFR-2 (HER2/erbB2) overexpression, accounts for 15–20% of all breast cancers and most commonly affects young women under the age of 45." (PMID 38072918, 2023). "Triple-negative breast cancer (TNBC), the type of the tumor in absence of expression of estrogen receptor (ER), progesterone receptor (PGR) and human epidermal growth factor receptor 2 (HER2) is a common and aggressive subtype of breast cancer with poorer prognosis and shortened survival duration." (PMID 36520265, 2022). "It is well known that triple-negative breast cancer, with the absence of estrogen receptor (ER), progesterone receptor (PR), and human epidermal growth factor receptor-type 2 (HER2), is a highly aggressive mammary tumor subtype, responsible for about 12–20% of all breast cancer cases." (PMID 36297448, 2022). "TNBC is estrogen receptor (ER), progesterone receptor (PR) and human epidermal growth factor receptor-2 (HER2) negative breast cancer, is not sensitive to common endocrine therapy and targeted therapy, has a poor prognosis, and is prone to early recurrence and metastasis." (PMID 35413833, 2022). "Patients who have breast cancer, especially triple-negative breast cancer (TNBC) lacking estrogen receptor (ER), progesterone receptor (PR), and human epidermal growth factor receptor 2 (HER2) benefit from pembrolizumab monotherapy and atezolizumab monotherapy significantly." (PMID 35912168, 2022).
breast cancer (continued). "Among molecular subtypes based on protein expression status, triple-negative breast cancer (TNBC), i.e., lack of expression in estrogen receptor (ER), progesterone receptor (PR), and human epidermal growth factor receptor 2 (HER2), accounts for up to 15% of breast cancer cases." (PMID 35406618, 2022). "A 50-year-old woman with a history of hypertension and diabetes presents with a T2N0M0 triple-negative (estrogen receptor [ER] negative, progesterone receptor [PR] negative, human epidermal growth factor receptor 2 [HER2] negative) breast cancer of the left breast." (PMID 35492817, 2022). "Breast cancer is divided into three subtypes for alignment with therapy options: estrogen receptor-positive, HER2-positive, and triple-negative (for a lack of estrogen receptor and progesterone receptor, and a lack of HER2 gene amplification) breast cancer." (PMID 35681611, 2022). "Histopathological tumor analysis identifies 15–20% of breast cancers cases as triple-negative breast cancer (TNBC), characterized by lack of expression of estrogen receptor, progesterone receptor, and low expression of human epidermal growth factor receptor (HER2)." (PMID 34439373, 2021). "Triple-negative breast cancers (TNBCs) are immunohistochemically defined as a subset of breast cancers that are negative for human epidermal growth factor receptor-2 (HER2), estrogen receptor (ER) and progesterone receptor (PR) and account for 15–20% of breast cancers." (PMID 33916322, 2021). "Approximately 15% of all breast cancers are triple-negative breast cancer (TNBC), which is estrogen receptor (ER)-negative, progesterone receptor (PR)-negative, and human epidermal growth factor receptor 2 (HER2)-negative; TNBC generally exhibits a more aggressive clinical presentation." (PMID 33911067, 2021). "As a specific subtype of breast cancer, triple-negative breast cancer (TNBC) is characterized by negative estrogen receptor (ER), progesterone receptor (PR) and human epidermal growth factor receptor 2 (HER-2), accounting for about 15 ~ 20 % of all breast cancer cases." (PMID 34006305, 2021). "Next, an in silico analysis showed that genes related to breast cancer, including HES1, MYC, CCND1, FOS and PGR, could be regulated by NRIP1 (data not shown)." (PMID 34707101, 2021). "Breast cancer, a hormone‐dependent tumour, generally includes four molecular subtypes (luminal A, luminal B, HER2 enriched and triple‐negative) based on oestrogen receptor, progesterone receptor and human epidermal growth factor receptor‐2." (PMID 34651424, 2021). "Triple-negative breast cancer (TNBC), a subset of breast cancer, accounts for the majority of breast cancer death due to the lack of specific treatment targets, as TNBC does not express estrogen receptor, progesterone receptor, and human epidermal growth factor receptor-22." (PMID 33414428, 2021). "The majority of breast carcinomas in macaques are of “Luminal A” type, expressing both ER and PGR; HER-2 overexpressing tumors have also been reported, and some carcinomas do not express ER, PGR and HER-2, known as “triple negative” as in humans." (PMID 33397518, 2021). "Furthermore, CENPU was markedly upregulated in patients with lymph node metastasis, as well as in estrogen receptor (ER)-negative, progesterone receptor (PR)-negative, and human epidermal growth factor receptor 2 (HER2)-positive breast carcinoma patients." (PMID 33902008, 2021). "Six of 88 breast cancers (7%) showed MSI, and then four of six had ER- and PgR negative features." (PMID 31907878, 2020). "In addition, based on their immunohistochemically determined receptor status, breast cancers have also been classified as ER and/or PgR positive type, HER2 positive type, and triple negative type (TNBC; ER and/or PgR negative, HER2 negative)." (PMID 32658903, 2020).